PRPH2 (peripherin 2)
Diseases named in the same sentence as PRPH2 in open-access papers (continued):
Sharing a sentence is not in itself a finding about the gene and the disease.
Macular dystrophy (continued). "For macular dystrophies, the most common gene by far was ABCA4 (autosomal recessive), whereas PRPH2 and BEST1 were implicated frequently in autosomal dominantly inherited macular dystrophies." (PMID 32423767, 2020). "We propose that the EZ thickness could be a useful biomarker for distinguishing PRPH2 retinopathy from other macular dystrophies." (PMID 41009962, 2025). "Patients carrying the C213Y mutation in PRPH2 display a butterfly-shaped pattern/macular dystrophy, while a rod dominant RP phenotype is absent." (PMID 32213850, 2020). "The clinical phenotype exhibits significant overlap with PRPH2-PD as well as other macular dystrophies, including AMD, which may explain the paucity of described cases in the literature." (PMID 30630813, 2019). "Although all our patients were diagnosed clinically with STGD, the overlapping of phenotypes between different macular dystrophies and several stages of ABCA4-associated retinopathy could result in a misdiagnosis of STGD with mutations in phenocopying genes, such as PRPH2, ROM1, CRX, or RPGR." (PMID 33841504, 2021). "Because of these many confounders, incomplete penetrance, variable expressivity, unknown family, adoption, consanguinity, early deaths, missed or false diagnosis, the inheritance pattern alone is not sufficient to distinguish between ABCA4-, ELOVL4- and PRPH2-linked macular dystrophies." (PMID 34073554, 2021). "Furthermore, the study highlighted the importance of sequencing of PRPH2 and ABCA4 genes since in several patients both genotype and a reevaluation of the phenotype pointed towards an inherited macular dystrophy, rather than AMD." (PMID 36108770, 2022).
Retinal dystrophy (28 papers, 2015 to 2025). Retinal dystrophy is an abnormality of the retina associated with a hereditary process. "PRPH2 gene mutations are a common cause of retinal dystrophies, together with AMD and diabetic retinopathy (DR)." (PMID 40170065, 2025). "On the other hand, other studies reported c.424C>T as a common causative variant in the European population associated with PRPH2-related retinal dystrophy with an autosomal dominant pattern." (PMID 40722607, 2025). "This variant was reported in patients with autosomal dominant PRPH2-associated retinal dystrophy and was also identified in our cohort, in a patient with a family history of RP." (PMID 40722607, 2025). "Inherited retinal dystrophies (IRD) associated with pathogenic or likely pathogenic variants in the PRPH2 gene are known to present with a broad clinical spectrum of retinal manifestations even within the same family." (PMID 40725586, 2025). "Background/Objectives: Pathogenic variants in the PRPH2 gene are implicated in a wide spectrum of Inherited Retinal Dystrophies (IRDs), which show significant phenotypic heterogeneity." (PMID 40722607, 2025). "Shankar and colleagues studied the PRPH2 pathogenic variant in 97 individuals and concluded that the c.828+3A>T PRPH2 splice site pathogenic variant has a founder effect and is a frequent cause of retinal dystrophies." (PMID 39610584, 2024). "Our findings also support that biallelic PRPH2 variants are responsible for more severe early-onset retinal dystrophy." (PMID 38474159, 2024). "PRPH2, one of the most frequently inherited retinal dystrophy (IRD)-causing genes, implies a high phenotypic variability." (PMID 38474159, 2024). "The peripherin gene (PRPH2) mutation is associated with photoreceptor cell dysfunction as well as in several inherited retinal dystrophies." (PMID 39298723, 2023). "There was evidence for an interaction effect between common genetic variants, VSX2 involved in eye development and PRPH2 known to be involved in retinal dystrophies." (PMID 36848389, 2023). "Variants in PRPH2 are a common cause of inherited retinal dystrophies with high genetic and phenotypic heterogeneity." (PMID 37047703, 2023). "PRPH2 gene mutations are frequently found in inherited retinal dystrophies (IRD) and are associated with a wide spectrum of clinical phenotypes." (PMID 36010202, 2022). "We analyzed 40 Japanese patients with PRPH2-associated retinal dystrophy and confirmed the genotypic and phenotypic variations of the disease in the Japanese population." (PMID 34828423, 2021). "In the present study, we report 40 Japanese patients from 30 families with PRPH2-associated retinal dystrophy." (PMID 34828423, 2021). "More than 90 pathogenic variants in PRPH2 are associated with retinal dystrophies, including retinitis pigmentosa punctate albescens." (PMID 33801777, 2021). "Here, we present the clinical and genetic features of 40 patients with PRPH2-associated retinal dystrophy." (PMID 34828423, 2021). "Most patients (from 16 families) had autosomal dominant inheritance of PRPH2-associated retinal dystrophy, whereas 11 patients had sporadic disease." (PMID 34828423, 2021). "Mutations in the corresponding PRPH2 gene cause different types of retinal dystrophies characterized by a loss of photoreceptors." (PMID 28723922, 2017). "Variants of PRPH2 have been reported to be a common cause of inherited retinal dystrophies." (PMID 37047703, 2023). "Peripherin-2 (PRPH2) is one of the causative genes of inherited retinal dystrophy." (PMID 34828423, 2021). "Concerning the variant c.121del (p.Leu41Ter), it was located in the exon 1 of PRPH2 and was found at the heterozygous state in a single patient (pt-3A) with a diagnosis of retinal dystrophy." (PMID 40722607, 2025). "While the variable phenotype and natural history of PRPH2- and OTX2-associated retinal dystrophies have been described in large cohorts, clinical features of CTNNA1-associated retinal dystrophy are less well studied." (PMID 40455352, 2025).
Retinal dystrophy (continued). "This study aimed to describe the intrafamilial phenotypic variability and natural history of a PRPH2-related retinal dystrophy." (PMID 39610584, 2024). "The contribution of PRPH2 has been reported to be 4.6% for inherited retinal dystrophies in European descendants and 3.6% for RP patients in Spain." (PMID 37047703, 2023). "By analyzing the 50° and 30° images we classified the PRPH2 retinal dystrophy spectrum and found common characteristics of seven different patterns." (PMID 36010202, 2022). "We identified four phenotypic subgroups similar to 1) mitochondrial retinopathy, 2) adult vitelliform or pattern dystrophy, 3) fundus dystrophy similar to LORD or Sorsby fundus dystrophy or 4) PRPH2- or ABCA4-related retinopathy." (PMID 29555955, 2018). "Because of the phenotype variability, the diagnosis is often delayed, and the real number of patients affected by PRPH2-related retinal dystrophy may be underestimated." (PMID 36010202, 2022). "In another family with 3 affected individuals and 1 presumed non-penetrant member, NGS identified three retinal dystrophy genes (PRPF8, PRPH2 and USH2A) with dis-ease-causing variants in varying combinations among the affected individuals." (PMID 40426944, 2025).
retinal diseases (23 papers, 2015 to 2025). "PRPH2 variants have been implicated in numerous inherited retinal diseases, including autosomal dominant retinitis pigmentosa." (PMID 40927123, 2025). "Overall, this retrospective case series strengthens the understanding of the long-term retinal disease progression in patients with a common PRPH2 pathogenic variant." (PMID 39610584, 2024). "Ultimately, our study comparing three different D2 loop cysteine mutations expressed alone and in combinations highlights two critical disease mechanisms relevant to the development of PRPH2-associated inherited retinal diseases." (PMID 37466729, 2023). "Although the exact genotype–phenotype correlation of PRPH2-associated retinal diseases is unclear, the exploration of genotype–phenotype correlations in this study provides further information." (PMID 37047703, 2023). "In this study, we analyzed the functional, structural, and biochemical consequences of PRPH2 D2 loop mutations, alone and in combination with each other in order to refine our framework for understanding mechanisms that cause retinal disease." (PMID 37466729, 2023). "Many inherited retinal diseases are linked to the more than 200 known pathogenic mutations in PRPH2." (PMID 37466729, 2023). "Class 1 included four missense variants that were predicted as damaging by at least six of seven in silico tools, were absent in the gnomAD database, and had been reported as causative for PRPH2-associated retinal diseases." (PMID 37047703, 2023). "Pattern dystrophies are usually a group of hereditary retinal diseases mostly related to PRPH2 gene variants, usually in an autosomal dominant inheritance although they can also present in an autosomal recessive inheritance." (PMID 34051736, 2021). "Retinal disease was detected from the third decade of life in all of them, as also described in other studies about this mutation and other mutations in PRPH2." (PMID 33925984, 2021). "Mutations in PRPH2 cause a multitude of retinal diseases including autosomal dominant retinitis pigmentosa (RP) or cone dominant macular dystrophies." (PMID 32213850, 2020). "In line with its key role in OS formation, mutations in PRPH2 are connected with a multitude of retinal diseases ranging from autosomal dominant retinitis pigmentosa (ADRP) to macular degeneration (MD)." (PMID 32213850, 2020). "Over 175 pathogenic mutations in the Peripherin-2 (PRPH2) gene are linked to various retinal diseases." (PMID 32660024, 2020). "We report the phenotype and genotype of eight families (24 patients) with retinal diseases associated with seven distinct PRPH2 gene mutations." (PMID 32660024, 2020). "The retinal disease phenotype of the presented case exhibits features consistent with late-onset PD, including a butterfly-like central lesion associated with PRPH2 and, more recently, recessive mutations in CTNNA1." (PMID 30630813, 2019). "PRPH2 gene is linked to the most heterogeneous spectrum of retinal diseases." (PMID 36833218, 2023). "Although Rom1−/− mice exhibit much milder phenotype than Prph2 knockouts, and retinal disease attributable to pathogenic mutations in ROM1 alone has yet to be described, ROM1 has been shown to play a significant role in OS biogenesis, especially in the maturation of the OS with PRPH2." (PMID 30630813, 2019). "The identification of novel variants reported herein expands the known genetic spectrum of PRPH2, contributing to improved molecular diagnosis and understanding of this complex retinal disease." (PMID 41009962, 2025). "The human Peripherin 2 (PRPH2) gene, essential for the structure and function of photoreceptor outer segments, is implicated in a range of inherited retinal diseases (IRDs)." (PMID 41210588, 2025). "In UK Biobank analyses, it detects 10.2% more blood-trait associations and reveals novel gene–disease links, including PRPH2 with retinal disease." (PMID 41136342, 2025).
retinal diseases (continued). "Since potent PARP inhibitors have been developed, we chose two approved inhibitors to facilitate translation into clinical trials for peripherin-2 related retinal diseases." (PMID 40170065, 2025). "In our study, we selected two approved inhibitors, Olaparib and BMN-673, to facilitate translation into clinical trials for peripherin-2-related retinal diseases, as well as 3-aminobenzamide, previously shown to be a potent PARP inhibitor." (PMID 40170065, 2025). "Beyond disease connections to STX3 mutations, the interaction of STX3 with PRPH2 and RHO suggest a broader impact on retinal diseases." (PMID 38799985, 2024). "The role of PRPH2 variation in dominant and recessive retinal diseases have been extensively studied, however, much less is known about its oligomerization partner, retinal outer segment membrane protein 1 (ROM1, OMIM #180721)." (PMID 35353811, 2022). "Variants in ABCA4, PRPH2, and BEST1 alone explained retinal disease in 60.7% of the MD cohort, similar to previously published results (57%)." (PMID 33546218, 2021). "In 57% of all MD/CCRD cases (77% of the 185 solved cases), retinal disease was explained by mutations in ABCA4 (n = 94, 37%), PRPH2 (n = 29, 12%) or BEST1 (n = 19, 8%; including 5 a.r. and 14 a.d. mutations)." (PMID 29555955, 2018). "Mutations in ABCA4, PRPH2 and BEST1 were predominant, explaining the retinal disease in 57% of the entire cohort and 74% of the solved cases." (PMID 29555955, 2018). "In the disease trait GWAS, BayesRVAT uniquely linked PRPH2 to AMD and other retinal diseases." (PMID 41136342, 2025). "Although progress has been made in the development of therapeutic approaches for retinal diseases in general, the highly complex interplay of functions mediated by Prph2 and the precise regulation of these complexes made it difficult, thus far, to develop a suitable Prph2-specific therapy." (PMID 32213850, 2020). "The second is a link between PRPH2 and AMD and other retinal diseases." (PMID 41136342, 2025). "The large number of inherited retinal disease genes (IRD), including the photopigment rhodopsin and the photoreceptor outer segment (OS) structural component peripherin 2 (PRPH2), has prompted interest in identifying common cellular mechanisms involved in degeneration." (PMID 33138244, 2020).
central areolar choroidal dystrophy (14 papers, 2014 to 2025). "A similarly located lesion has been observed in one eye of an unrelated patient associated with the p.(Arg172Gln) variant in the PRPH2 gene; the other eye of that patient presented with a perifoveal lesion similar to central areolar choroidal dystrophy." (PMID 40725586, 2025). "Both multifocal pattern dystrophy and central areolar choroidal dystrophy are associated with mutations of the PRPH2 gene with autosomal dominant inheritance." (PMID 24906873, 2014). "In three (1.4%) of 218 cases we identified a pathogenic heterozygous variant (PRPH2 c.424C > T; p.R142W) causal for autosomal dominant central areolar choroidal dystrophy (CACD)." (PMID 30215852, 2018).
Stargardt disease (12 papers, 2012 to 2025). "In our study, we compare the diagnostic accuracy of four different MLLMs to differentiate PPS Maculopathy, Stargardt Disease, and PRPH2-associated pattern dystrophy." (PMID 41339423, 2025). "The study included 126 eyes from 63 patients, with 36 eyes with PPS maculopathy, 50 eyes with Stargardt disease, and 40 eyes with PRPH2-associated multifocal pattern dystrophy." (PMID 41339423, 2025). "The presence of rare, coding PRPH2 variants in STGD cases with one or more ABCA4 mutations suggests that one must be cautious regarding attributing apparent cases of Stargardt Disease to ABCA4 mutations when only ABCA4 has been screened." (PMID 22863181, 2012). "Boon and colleagues demonstrated that different PRPH2 pathogenic variants could be present with multifocal pattern dystrophy simulating Stargardt disease." (PMID 39610584, 2024). "Many patients with PRPH2 mutation present with a phenotype similar to late-onset Stargardt disease." (PMID 29555955, 2018). "From a clinical perspective, early molecular diagnosis of PRPH2-related disease could help to differentiate it from conditions with similar phenotypes, such as age-related macular degeneration or Stargardt disease." (PMID 40722607, 2025). "The phenotypic intersection between Stargardt disease and PD is also apparent from a histopathological study of a PRPH2 p.Cys213Tyr PD donor eye, finding that RPE cells were distended with lipofuscin much in an analogous manner to donor eyes with defective ABCA4." (PMID 30630813, 2019). "The most important differential diagnoses of atrophic late AMD are the gene ABCA4, PRPH2, and BEST1 inherited macular dystrophies, including Stargardt disease (STGD1), Best disease (BD), or pseudo-Stargardt multifocal pattern dystrophy (PSPD) in late atrophic stages." (PMID 38132220, 2023).
cone-rod dystrophy (10 papers, 2015 to 2024). Inherited retinal dystrophies that belong to the group of pigmentary retinopathies. "Pathogenic variants of PRPH2 may cause diverse phenotypes such as retinitis pigmentosa (RP), retinitis punctata albescens, cone/cone-rod dystrophy (CRD), and macular dystrophies (MD)." (PMID 34828423, 2021). "These include macular diseases such as age-related macular dystrophy and cone-rod dystrophies such as foveal sparing ABCA4 retinopathy and certain PRPH2 retinopathies." (PMID 35806404, 2022).
vitelliform macular dystrophy (10 papers, 2015 to 2024). A rare genetic disorder characterized by macular degeneration in the retina resulting in progressive loss of central vision with retention of the peripheral vision. "Two patients were diagnosed with adult vitelliform macular dystrophy (AVMD) caused by one PRPH2 variant in conjunction with one potential pathogenic variant in ROM1." (PMID 37047703, 2023). "Adult-onset foveomacular vitelliform dystrophy (AOFVD) is a subtype of macular pattern dystrophies, being associated with mutations in the peripherin 2 (PRPH2) gene, either sporadic or inherited in an autosomal dominant manner." (PMID 27190637, 2016).
Leber congenital amaurosis (9 papers, 2015 to 2025). Leber congenital amaurosis (LCA) is a retinal dystrophy defined by blindness and responses to electrophysiological stimulation (Ganzfeld electroretinogram (ERG)) below threshold, associated with severe visual impairment within the first year of life. "Patients with Leber congenital amaurosis (LCA: OMIM 608133) have been reported with homozygous PRPH2 mutations." (PMID 41009962, 2025).
autosomal dominant retinitis pigmentosa (8 papers, 2013 to 2025). Autosomal dominant retinitis pigmentosa (RP) is an autosomally dominant inherited retinal dystrophy leading to progressive loss of the photoreceptors and retinal pigment epithelium and resulting in blindness usually after several decades. "Mutations in the photoreceptor outer segment (OS) specific peripherin-2 lead to autosomal dominant retinitis pigmentosa (adRP)." (PMID 28539581, 2017). "The autosomal dominant retinitis pigmentosa (adRP) phenotype has been reported to account for 9.6–40% of PRPH2 retinopathy cases." (PMID 41009962, 2025).
Blindness (4 papers, 2014 to 2025). Blindness is the condition of lacking visual perception defined as a profound reduction in visual perception. "Our Cryo-ET data provide novel quantitative and structural information on the molecular architecture in ROS and substantiate previous results on proposed mechanisms underlying pathologies of certain PRPH2 mutations leading to blindness." (PMID 34931611, 2021). "High-risk PRPH2 and ROM1 mutations causing blindness map to the protein-dimer interface." (PMID 36351012, 2022).
macular degeneration (4 papers, 2008 to 2024). Loss of vision in the central portion of the retina (macula), secondary to retinal degeneration. "The proband’s mother, who also carried the variant p.Gly208Asp in PRPH2, was diagnosed with macular degeneration at 60 years old." (PMID 38474159, 2024). "The PRPH2 mutation may play a role in macular edema and PRD, as it is implicated in macular degeneration, choroid defects, and photoreceptor dysfunction." (PMID 38860019, 2024).
macular pattern dystrophies (4 papers, 2012 to 2021). "ROM1 and PRPH2 pattern macular dystrophies exhibit phenotype overlap, which may be attributable to their shared role in maintenance of the photoreceptor outer segment structure." (PMID 30630813, 2019).
Atrophy (3 papers, 2021 to 2024). Any weakening or degeneration, especially through lack of use. "In the small number of patients harboring the pathogenic PRPH2 variant, we could observe both “flecks” and “atrophy” clinical phenotypes." (PMID 34073554, 2021). "CACD (CACD1, GUCY2D, OMIM #600179: autosomal dominant; CACD2, PRPH2, OMIM 179605: autosomal dominant) presents with a well-demarcated area of atrophy of the RPE and choriocapillaris, usually centered in the macula." (PMID 38610844, 2024).